HBA2 (hemoglobin subunit alpha 2)
Diseases named in the same sentence as HBA2 in open-access papers (continued):
Sharing a sentence is not in itself a finding about the gene and the disease.
Alpha-thalassemia (34 papers, 2012 to 2025). Alpha-thalassemia is an inherited hemoglobinopathy characterized by impaired synthesis of alpha-globin chains leading to a variable clinical picture depending on the number of affected alleles. "In contrast, the AUC and Youden index of MCH were 0.912 and 0.6841, respectively, which were significantly higher than those of MCV and HbA2, indicating that this parameter had a higher diagnostic value for alpha-thalassemia." (PMID 40758675, 2025). "Deletion at 16p13.3 includes the loss of multiple genes including HBA1 and HBA2 resulting in alpha thalassemia phenotype, however the genes responsible for ID and other development abnormalities are not yet clearly identified." (PMID 28935972, 2017). "A similar scenario has been put forward for rearrangements associated with the alpha-globin gene family, where recurrent deletions of HBA1 and HBA2 associated with alpha-thalassemia have reached a high frequency in Mediterranean and Pacific populations." (PMID 23594316, 2013). "Similarly, 5 major haplotypes are identified in HBA1/HBA2 homologous region while one of them is found highly linked with deletional α‐thalassemia mutations." (PMID 39737841, 2025). "One case was homozygous for the HBA2 variant [NM_000517.6: c.377T>C(p.Leu126Pro)], which was inherited from both parents, and was diagnosed with alpha thalassemia; the other patient carried a de novo GNAS variant [NM_000516.7: c.139G>A(p.Gly47Ser)] and was diagnosed with pseudohypoparathyroidism Ia." (PMID 38764027, 2024). "Although HPLC has more advantages, it should be noted that lowered HbA2 values may be measured due to errors caused by the co-elution of HbS and HbA2, analytic references, alpha thalassemia, iron deficiency or delta gene mutations." (PMID 35291497, 2022). "Since both iron deficiency and α+-thalassemia trait are common and both lower the level of HbA2, this decrease in HbA2 may cause some BTT carriers to be missed on screening." (PMID 23577263, 2013). "The deletion HBA2 gene would have greater impact in the generation of the alpha-thalassemia phenotype, in comparison to deletion HBA1." (PMID 41262547, 2025). "In practice, mean corpuscular volume (MCV), mean corpuscular hemoglobin (MCH) and hemoglobin A2 (HbA2) were the most commonly used to screen for alpha-thalassemia." (PMID 40758675, 2025). "A lower MCHC is associated with alpha thalassaemia, resulting from deletions in HBA1 and HBA2 genes." (PMID 40446072, 2025). "The AUC of HbA2 was 0.761 (P < 0.05, 95% CI was 0.752 ~ 0.769), and the best cutoff value to predict alpha-thalassemia was 2.55, giving a Youden index of 0.4199." (PMID 40758675, 2025). "The sensitivity and false-positive rate were 78.51% and 36.52%, and the positive likelihood ratio was 2.1499, indicating that the positive screening results of HbA2 had a poor effect on the diagnosis of alpha-thalassemia." (PMID 40758675, 2025). "On the other hand, alpha thalassemia is mainly attributed to deletions in the alpha hemoglobin locus 1 (HBA1) (OMIM *141800) or alpha hemoglobin locus 2 (HBA2) (OMIM *141850)." (PMID 38535125, 2024). "Subsequent NGS analysis uncovered a whole-gene deletion of HBA1 and HBA2, alongside an LP/P variant in PIEZO1, leading to a conclusive diagnosis of alpha thalassemia minor combined with dehydrated hereditary stomatocytosis." (PMID 37697358, 2023). "HBA1/HBA2‐genotyping was performed in 207 children (53%), and α‐thalassemia was diagnosed in 47 children (23%) with −α3.7/αα being the predominant genotype (13%)." (PMID 36819175, 2023). "α0-thalassemia is usually caused by large deletions covering both HBA2 and HBA1 genes; however, α+-thalassemia can be caused by either an additional mutation that affects only a single HBA gene or a point mutation that reduces α-globin chain production." (PMID 37330590, 2023).
Alpha-thalassemia (continued). "The HbA2 level was very similar in the non‐α‐thalassemia group (N = 80) and in the α‐thalassemia children with two and three functional α‐genes (N = 33) while the HbA2 level in the two children with only one functional α‐gene was very low." (PMID 36819175, 2023). "If both Hba1 and Hba2 genes were affected by the Cre/lox recombination, severe alpha thalassemia would be induced, resulting in embryonic lethality." (PMID 36302779, 2022). "However, due to the identical length of the HBA1 and HBA2 genes, sequencing analysis for alpha-thalassemia has been challenging." (PMID 40523316, 2025). "The alpha-thalassemia (alpha-thal) is the most common genetic disorder in the human population and is caused by the decreased or absent synthesis of the alpha globin chain due to the deletion or nondeletion mutation of one or both alpha-globin genes (HBA1 and HBA2), located on chromosome 16." (PMID 23316245, 2012). "Normal HbA2 and HbF fractions, both by HPLC and capillary electrophoresis, reinforce the importance of considering alpha thalassemia in cases of unexplained microcytosis, even in the absence of family history." (PMID 41009357, 2025). "In summary, this study revealed a novel 9.159-kb HBA2 gene deletion through SMRT sequencing in a Chinese family, resulting in mild alpha + -thalassemia phenotype." (PMID 41262547, 2025). "For instance, in the case of alpha thalassemia, the highly homologous sequences between HBA1 (NM_000558.5) and HBA2 (NM_000517), pose challenges in accurate identification." (PMID 38982507, 2024). "Age of ‐‐SEA/αα was lower than that of ‐α3.7/αα and ‐α4.2/αα (p < 0.05) Among the non‐deletional genotypes of α‐thalassemia, patients with αQSα/αα were found to have higher RBC and HbA2 and lower MCV and MCH than patients with αCSα/αα (p < 0.05)." (PMID 36099017, 2022). "In negative-for-alpha-thalassemia group, 12038 participants were tested for MCV, MCH and HbA2 simultaneously, 1162 participants were tested for MCVand MCH only, 430 participants were tested for HbA2 only." (PMID 40758675, 2025).
beta thalassemia (22 papers, 2010 to 2025). Beta-thalassemia (BT) is characterized by deficiency (Beta+) or absence (Beta0) of synthesis of the beta globin chains of hemoglobin (Hb). "LoF variants in SUPT5H are associated with a beta-thalassemia-like phenotype in so-called unlinked beta-thalassemia cases with typically elevated HbA2 and, in most cases, microcytic hypochromic erythrocyte parameters." (PMID 39201615, 2024). "High-performance liquid chromatography (HPLC) was indicative of a compound heterozygous for beta-thalassemia and HbS (HbS-76%, HbA2-5.3%, HbA-7.7%), and other investigations, such as serum homocysteine, iron profile, and coagulation profile, were normal." (PMID 40525054, 2025). "Peripheral smear showed sickle cells; high-performance liquid chromatography indicated sickle beta thalassemia (HbS 76%, HbA2 5.3%, HbA 7.7%)." (PMID 40525054, 2025). "Some studies have shown that iron deficiency results in reduced synthesis of HbA2, which could result in normal HbA2 levels, although other studies have refuted this assumption; however, it is important to screen for and correct any iron deficiency before beta thalassemia screening is undertaken." (PMID 38975448, 2024). "The cutoff value of hemoglobin A2 (HbA2) to diagnose beta-thalassemia trait can vary slightly depending on the laboratory and the population being studied." (PMID 38716362, 2024). "The haplo-insufficiency of Spt5, or a truncated Spt5 which misses the carboxy-terminus, is apparently the mechanism which gives rise to the typical phenotype of beta-thalassemia traits with the characteristically elevated levels of HbA2." (PMID 39201615, 2024). "Nonetheless, carriers of sickle-cell anemia and beta-thalassemia have, on average, higher HbF and HbA2 levels." (PMID 39056767, 2024). "Beta thalassemia minor, in which HbA2 or the sum of HbA2 and HbA2’ was 3.5% or more, was found among 2% of both women and children." (PMID 37468973, 2023). "Second, if hypochromic microcytic RBCs or poikilocytosis are observed, Hb HPLC is performed to identify HBA2, HbF, or other Hb fractions, which are frequently observed in alpha or beta thalassemia." (PMID 36832257, 2023). "The assessed higher prevalence of alpha-thalassaemia among the beta-thalassaemia carriers (25.3%) seems to be closer to the true prevalence in the population and it is higher than that estimated only by the low percentage of HbA2 (16.9%)." (PMID 29181452, 2017). "The presence of elevated levels of Haemoglobin A2 (HbA2) in those samples is the gold standard used to identify definite carriers of beta thalassaemia in the second stage of the screen." (PMID 25521998, 2015). "The elevated levels of HbA2 in the absence of a beta-thalassemia trait causing variants in the HBB gene is one of the most suggestive elements to identify variants in the SUPT5H gene." (PMID 39201615, 2024). "Heterozygotes may present either near-to-normal hematology or microcytic hypochromic parameters, but all were observed to have elevated HbA2 levels comparable to those in beta-thalassemia traits." (PMID 39201615, 2024). "In beta-thalassemia carriers expressing a more severe clinical phenotype than expected from beta-thalassemia traits, such elevated HbA2 percentages might be an indication for a co-inherited SUPT5H variant." (PMID 39201615, 2024). "For example, HPLC is highly useful in identifying carriers of beta thalassemia due to the significant increase of HbA2 increase, which compensates for the poor synthesis of beta chains and is one of the most important markers of beta thalassemia carrier status." (PMID 37868262, 2023). "HbA2 levels (> 3.5%) are the most significant parameter for identifying beta thalassemia carriers." (PMID 34633587, 2021). "Therefore, HbA2 determination should always be performed for betathalassemia carrier identification." (PMID 20492708, 2010).
beta thalassemia (continued). "The genetic complexity of the beta thalassemia trait is documented by its phenotypic heterogeneity, such as in cases with a: a) normal MCH and increased HbA2%; b) reduced MCH and HbA2 normal and c) reduced MCH and HbA2 increased." (PMID 30050878, 2017). "Between August 2012 and August 2013, alpha deletional mutations were analysed by PCR on 354 women presenting with a low percentage of HbA2 (≤2.2% by HPLC or ≤2.1% by CE) and on 159 women with beta-thalassaemia trait." (PMID 29181452, 2017). "This study was conducted on 164 subjects including 82 healthy ones and 82 patients with beta thalassemia minor (microcytosis (MCV <80 fl) and hypochromia (MCH <25 pg) and HbA2 ≥ 3.5% using HPLC)." (PMID 23497547, 2012). "Among patients with normal iron studies or a compatible family history, gel hemoglobin electrophoresis has been used to rule in or rule out beta thalassemia subtypes by the detection of elevated levels of hemoglobin A2 (HbA2)." (PMID 40084327, 2025). "Several erythroid-specific genes have been reported to carry variants causing elevation of the percentage of HbA2, such as GTF2E2, GATA1, ASH1L and KLF1, although not necessarily with beta-thalassemia traits like red cell indices." (PMID 39201615, 2024). "The therapeutic potential of delta-globin, the non-alpha component of Hemoglobin A2 (α2δ2; HbA2), has been demonstrated in a mouse model of beta thalassemia, while its anti-sickling effect, comparable to that of gamma globin, was established some time ago." (PMID 32528964, 2020). "Typical beta-thalassemia carriers are identified by analysis of RBC indices, which shows microcytosis (low MCV) and reduced content of Hb per red cell (low MCH), and by qualitative and quantitative Hb analysis, which displays the increase of HbA2." (PMID 20492708, 2010).
iron deficiency (17 papers, 2009 to 2025). "When iron deficiency was defined as ferritin <30 μg/L, iron deficient individuals (138/379) had a mean HbA2 (2.39 ± 0.25%) that was 0.11% lower than in individuals without iron deficiency (2.50 ± 0.24%, P < 0.0001)." (PMID 23577263, 2013). "Consequently, IDA commonly presents with a decrease in HbA2, likely due to the more pronounced impact of iron deficiency on δ-globin synthesis and potentially reduced α-globin availability." (PMID 41155185, 2025). "Several studies have shown that iron deficiency directly affects the rates of HbA2 synthesis in bone marrow; therefore, 16–20 weeks of iron therapy should be instituted, after which a repeat serum iron with electrophoresis is done to confirm improvement in the HbA2 levels." (PMID 24818016, 2014). "Therefore, subjects with iron deficiency and HbA2 between 3.2% and 3.5% could theoretically have BTT, that is, a false negative test." (PMID 23577263, 2013). "There was a significant statistical difference among those with iron deficiency, normal iron status, and iron overload in terms of hemoglobin level (P=0.001), RBC count (P=0.012), HbA2 (P=0.015), and serum ferritin (P < 0.0001)." (PMID 38975448, 2024). "Among 12 informative cases of BTT, five with iron deficiency (ferritin < 15 μg/L) had lower mean HbA2 (5.24 ± 0.23%) than seven without iron deficiency (5.41 ± 0.45%, P = 0.45)." (PMID 23577263, 2013). "However, a normal concentration of HbA2 does not rule out β-thalassemia trait, especially if there is concomitant iron deficiency, which can lower HbA2 levels into the normal range." (PMID 39062234, 2024). "Studies have shown that iron deficiency lowers (while iron repletion increases) HbA2; thereby, the diagnosis from non-BTT carrier may change to BTT carrier and vice versa (reviewed in 1)." (PMID 23577263, 2013).
hemoglobinopathies (16 papers, 2009 to 2025). "WES confirmed the pathogenic HBA2 mutation consistent with Hb Sun Prairie, highlighting the importance of molecular diagnostics in suspected rare hemoglobinopathies." (PMID 41473418, 2025). "CE also showed elevated levels of HbA2 at 3.6%–4.5%, a common finding in unstable β‐chain haemoglobinopathies." (PMID 39262298, 2024). "The main purpose of this study is to compare the performance of various in silico predictors and determine the most appropriate ones for predicting the functional impact of short nucleotide variants (SNVs) in HBA1, HBA2, and HBB related to haemoglobinopathies." (PMID 36453528, 2022). "The implementation of genotyping to screen hemoglobinopathies in 2014 necessitated readjustment of the borderline HbA2 cut-off between 3.2% to 3.5% within the scope of the program." (PMID 34683121, 2021). "Thus, in total, there were 37.6% (n38) pregnant women with suspected β-TT or other hemoglobinopathies, and these women were further suggested to be checked for HbA2 analysis in a referral laboratory in other cities for confirmation because this area was of limited resource area." (PMID 31772773, 2019). "Routine hemoglobinopathy screening was performed including CBC, HbF and HbA2 measurement by cation exchange HPLC and capillary electrophoresis (CE)." (PMID 39713528, 2024). "Collectively, our findings emphasize the need to offer molecular screening of the β globin gene to partners of carriers of hemoglobinopathies, irrespective of their hematological indices and HbA2 levels, to avoid a misdiagnosis of these “at-risk” couples who, in turn, could have affected children." (PMID 35354866, 2022). "We strongly suggest that a comprehensive molecular work up of the β globin gene should be performed when borderline HbA2 levels, in combination with normal/subnormal MCV and MCH values, are encountered in the routine laboratory setting in cases where one partner is a carrier of a hemoglobinopathy." (PMID 35354866, 2022). "As a result of limited diagnostic potential using high-performance liquid chromatography (HPLC), as it may not detect high oxygen affinity hemoglobinopathies, our NGS panel includes mutations in α- or β-globin genes (HBB, HBA1, HBA2) and the use of HPLC is not part of our algorithm." (PMID 35743463, 2022).
malaria (6 papers, 2013 to 2025). Malaria is a serious and sometimes fatal disease caused by a parasite that commonly infects a certain type of mosquito which feeds on humans. "We have now tested it on data of the HBA2 gene which, by the experimental design used in a malaria association study in Tanzania, shows a high missing data percentage and is weakly linked with the remaining genetic markers in the data set." (PMID 24942080, 2014). "However, using the best imputation model for the data, we obtained unbiased estimates for the genetic effects, and association signals of the HBA2 gene on malaria positivity." (PMID 24942080, 2014). "Consistent with GO annotations, the KEGG pathway “malaria” was enriched, accompanied by a decreased level of HBA2, suggesting reduced heme/oxygen binding." (PMID 39562369, 2025). "The HBA2 locus seems in Hardy-Weinberg equilibrium in most villages with the exception of Kadando, Tamota, Mgila, and Mgome where malaria tends to exert a higher selective pressure." (PMID 24942080, 2014). "Variants in genes residing in these loci (i.e., HBB, HBA1/HBA2, and G6PD) confer resistance to malaria." (PMID 23696099, 2013). "Variants in genes residing at these three loci (HBB, HBA1/HBA2, and G6PD) confer resistance to malaria in Africans." (PMID 23696099, 2013). "In this study, we identified genes related to the malaria resistance pathway (KEGG: hsa05144), including CCL2, CD40, HBA1, and HBA2 as the differential genes in DAI, indicating different selective pressure posed by malaria on the DAI compared to other M.Yunnan.West." (PMID 35864541, 2022).
sickle cell disease (6 papers, 2015 to 2024). Sickle cell anemias are chronic hemolytic diseases that may induce three types of acute accidents: severe anemia, severe bacterial infections, and ischemic vasoocclusive accidents (VOA) caused by sickle-shaped red blood cells obstructing small blood vessels and capillaries. "We studied the association of microRNA-423 with hemoglobin variables HbA1, HbA2, HbF and HbS of the patients with sickle cell disease were compared with the 3 genotypes (AA, AC and CC) of miR-423." (PMID 35735616, 2022). "In sickle cell disease however, due to the effects of the mutation on the properties of the β chain, the relationship between HbF and HbA2 levels, and with it the effect of genetic HbF modifiers on HbA2 levels, is fundamentally altered." (PMID 35844678, 2021). "However, except for one SNP 3’ to HBB that was downstream of 3’ HS-1 and the 3D enhancer that had an independent effect on HbA2 in sickle cell anemia, the association was mediated through the effect of these loci on HbF level." (PMID 26215470, 2015). "The hemoglobin electrophoresis realised for her mother concluded a heterozygous sickle cell anemia (HbS 35, 2%, HbA 60.8%, HbA2 3%, HbF 1%)." (PMID 26327979, 2015). "Perhaps by independently down-regulating expression of the HBA1/HBA2 genes, variants tagged by this NPRL3 SNP reduce hemolysis in sickle cell anemia." (PMID 26215470, 2015). "Two studies, one in a normal population and the other in sickle cell anemia, showed that BCL11A, the HBS1l-MYB interval and variants in HBB were associated with HbA2 level." (PMID 26215470, 2015). "The hemoglobin electrophoresis found a homozygous sickle cell disease (HbS: 78.5%, and 18.1% HbF, HbA2 3.4%)." (PMID 26327979, 2015).